MICB (MHC class I polypeptide-related sequence B)
Diseases named in the same sentence as MICB in open-access papers (continued):
Sharing a sentence is not in itself a finding about the gene and the disease.
cancer (continued). "For the targeting of MICA and MICB in cancer patients, we generated anti-MICA and MICB antibodies, by immunizing mice with recombinant soluble human MICA-Fc recombinant protein or a range of human C1R cells negative for endogenous MICA and MICB expression and engineered to express MICA alleles." (PMID 35967081, 2021). "However, advanced cancers frequently escape this immune mechanism by proteolytic shedding of cell surface-bound MICA and MICB molecules through the coordinate action of ERp5 and several cell surface proteases." (PMID 33789714, 2021). "The metastasis-associated miR-10b directly targets the 3′-UTR of MICB, but not MICA, and downregulates its expression in several cancer cell lines, impairing the ability of NK cells to recognize and eliminate tumor cells." (PMID 32316552, 2020). "Indeed, transient RNAi-mediated silencing of ADAM10 or ADAM17, or both, in distinct cancer cell lines revealed a considerable heterogeneity with regards their role in the proteolytic cleavage of MICA and MICB." (PMID 32269567, 2020). "Vγ9 Vδ2 T cells can recognize phosphorylated antigens that accumulate in cancer cells, interact with the F1-ATPase expressed at the cancer cell surface, and recognize stress-induced molecules, such as the MHC class I chain-related molecules A and B (MICA and MICB), as well as UL16-binding proteins." (PMID 29316940, 2018). "MICB expression on a large cohort of CRC patients uncovered its significantly lower expression in the cancer group compared to the control group, non-significantly lower expression in the metastatic group, and weakly significantly lower expression in the KRAS-positive group." (PMID 37869102, 2023). "In addition, CCNA2 could positively regulate TAP1, TAP2, CD276, MICB, PVR, and ULBP1 in almost all the cancer types." (PMID 35401923, 2022). "In addition, the use of HDACi was reported to have the immunomodulatory effect on NKG2D system, and was able to reverse the RT-insensitive cancer cells with DNA damage-dependent NKG2D ligands, MICA/MICB-, to MICA/MICB+ cells as well as sensitize these cells for NK cell mediated cytotoxicity." (PMID 36185276, 2022). "In addition, this study has also identified a new role of miRNAs in regulating MICB expression via 5′-UTR and provides information for further study on novel mechanisms of cellular miRNAs in regulation at the transcriptional level applicable for cancer immunotherapy." (PMID 28850101, 2017). "The analysis of 46 immunostimulatory genes in pan-cancer showed that HSP90B1 expression was positively correlated with CD40, CD270, PVR, MICB, ULBP1, TNFSF4, while exhibiting a negative correlation with CD48 and CD40LG in most cancers." (PMID 38243263, 2024). "In terms of immune-activated genes, AURKA exhibited positive correlations with MICB, PVR, CD276, and ULBP1 and negative correlations with C10orf54 in most cancers." (PMID 37965456, 2023).
infection (22 papers, 2009 to 2025). The state of being infected such as from the introduction of a foreign agent such as serum, vaccine, antigenic substance or organism. "The missense MICB variant associated with SARS-CoV-2 symptomatic infection, MICB*004 and rs3131639/A, is clearly overrepresented in symptomatic patients compared to both exposed seronegative and the general population." (PMID 34650566, 2021). "Among the genes related to immune modulation, we detected variants in MICA and MICB associated with symptomatic infections." (PMID 34650566, 2021). "Conversely, variants associated with lower MICB expression, possibly implicating a diminution of NK cytotoxicity, may facilitate infection." (PMID 34650566, 2021). "We hypothesize that individuals prone to produce higher amounts of sMICA, and low amounts of MICB, would be more susceptible to symptomatic infections." (PMID 34650566, 2021). "NKG2 receptors, including NKG2A, NKG2C, and NKG2D, are C-type lectin-like receptors that bind to HLA-E or stress-induced ligands like MICA/MICB, modulating NK cell activation in response to infection or malignancy." (PMID 41153412, 2025). "MICA and MICB variants were previously associated with SARS-CoV-2 infection, especially with symptomatic infections." (PMID 41153412, 2025). "MICA and MICB genes were transcribed by macrophages with higher expression at the 24 hours after infection time point." (PMID 39836471, 2025). "We recently studied HHV-6B, a closely related β-herpesvirus, which targets ULBP1, ULBP3 and MICB during infection." (PMID 34721381, 2021). "As MICB, ULBP1 and ULBP3 are downregulated following infection, we aimed to see if infected cells are less susceptible to NKG2D-dependent recognition by NK cells." (PMID 34721381, 2021). "Here, the regulatory MICA variant associated with symptomatic infection is related to higher mRNA expression, possibly higher soluble MICA (sMICA), while the opposite is observed for all MICB variants (supplementary results)." (PMID 34650566, 2021). "Whereas 64% of mock-infected A673 cells expressed MICA/MICB (mock infection), 51% of A673 cells expressed MICA/MICB after MeV-GFP infection at 48 hpi (infection with MeV-GFP)." (PMID 31795974, 2019). "Moreover, MICA and MICB, ligands for NKG2D, are induced upon cellular stress during pathogenic infection and NKG2D on decidual NK cells is involved in cytotoxic killing of virus-infected decidual fibroblasts." (PMID 38571943, 2024). "While infection with a UL16 deletion mutant caused the expected increase in MICB and ULBP2 cell surface expression, deletion of UL142 did not have a similar impact on its target, MICA." (PMID 24787765, 2014). "MICA and MICB are Class I MHC-related glycoproteins that are upregulated on the surface of cells in response to stress, for instance due to infection or malignant transformation." (PMID 38550583, 2024). "Using cell-culture based infection models, we found that H. pylori infection of stomach epithelial cells induced both gene expression and soluble release of the NKG2D-Ls MICA and MICB and reduced MICA/B cell surface expression." (PMID 38318189, 2024). "Next, we evaluated the expression levels of the NKG2D ligands MICA, MICB and ULBP1-3 at 48 hrs post-infection." (PMID 37753084, 2023). "For instance, the OR for MICB*004 and HLA-DOB*01:02 for symptomatic infection is 2.8 and 7.39, respectively." (PMID 34650566, 2021). "Twenty-four hours following infection, we stained the mock-infected and the infected cells for the expression of NKG2D ligands: MICA, MICB, ULBP1, ULBP2, ULBP3, and ULBP4." (PMID 32698530, 2020). "We demonstrate that the infected cells respond to the infection and that, upon infection, the mRNA and the total protein amount of MICA, MICB, ULBP2, and ULBP3 are upregulated." (PMID 32698530, 2020).
infection (continued). "One of the key receptors for NK cell activation is NKG2D that has multiple ligands, including MICA, MICB, and ULBP, which are preferentially expressed following cellular stress, infection, or DNA damage." (PMID 27816971, 2016). "Therefore, we monitored glycosylation of MICB over 24 h of infection by collecting cells at various hpi and digesting cell lysates with Endoglycosidase H (EndoH) or Peptide N-Glycosidase F (PNGaseF) prior to electrophoretic separation and immunoblot with MICB-specific antibodies." (PMID 27580123, 2016). "Genes that were down-regulated genes at 24h post infection included inflammatory and anti-pathogen genes (CSF1 and USP2) and the cell apoptosis and death genes (MICB, BUB1B, ITGB2, UBB and BIRC3)." (PMID 23527143, 2013). "Infection with the ΔcagA and ΔcagL mutants resulted in only slightly lower levels of MICA and MICB mRNA expression, whereas infection with the ΔvacA mutant resulted in greatly lower levels of MICA and MICB mRNA expression, compared to infection with the WT." (PMID 38318189, 2024). "Intracellular protein levels of MICA, MICB, ULBP2, and ULBP3 were tested 48 hrs post-infection." (PMID 37753084, 2023). "Shedding of MICA, ULBP2, and ULBP3 was not enhanced post-infection, whereas shedding of MICB was reduced." (PMID 37753084, 2023). "Interestingly, we observed a strong decrease of all MICB, ULBP1 and ULBP3 total protein following infection with HHV-6A (quantified in the bar diagram) indicating that there is no intracellular retention, but actual reduction in overall protein levels." (PMID 34721381, 2021). "MICA, MICB, ULBP2, and ULBP3 were upregulated following infection with both HMPV/WT and HMPV/ΔG." (PMID 32698530, 2020). "In contrast to RhCMV-infected U373-MICB cells, MICB acquired EndoH resistance upon infection with ΔRh159 at the same rate as observed for uninfected cells suggesting that intracellular transport of MICB was no longer inhibited." (PMID 27580123, 2016). "Since MICA, MICB, and ULBP2 surface levels were significantly higher in cells infected with ΔRh159 compared to RhCMV, we wanted to specifically address the impact of Rh159 on the maturation of these NKG2DLs when newly synthesized during infection." (PMID 27580123, 2016). "Similarly, MICB was first downregulated at 36 hrs post-infection; however, we did not observe a further decrease in expression at later time points." (PMID 37753084, 2023). "In characterising the up regulation of NKG2DL, we identified a differential effect on MICA and MICB by the HCMV IE gene products, and yet HCMV immune evasion functions were effective in preventing surface expression of these NKG2DL through the early phase of lytic infection." (PMID 24787765, 2014). "We set out to determine whether the rapid up regulation of NKG2DL transcription driven by expression of the major HCMV IE genes would result in transient exposure of the activating ligands MICA, MICB, or ULBP2 early during infection, thereby creating a window of opportunity for NK cell recognition." (PMID 24787765, 2014). "As the block deletion mutants were made on a ΔUL16ΔUL18 background, the parental HCMV control up regulated MICB and ULBP2 relative to mock-infected cells, whereas the ΔUS18–22 mutant up regulated cell surface levels of MICA relative to both mock- and parental HCMV-infections." (PMID 24787765, 2014). "Importantly, H. pylori WT infection resulted in significantly increased MICA and MICB mRNA levels compared to non-infected cells, and induction increased over time." (PMID 38318189, 2024).
MICB also shares sentences with these, for which no sentence is quoted: gastric cancer (5 papers); systemic lupus erythematosus (4); AIDS (2); B-cell lymphoma (2); cholangiocarcinoma (2); diabetes (2); hypothyroidism (2); lung adenocarcinoma (2); oral squamous cell carcinoma (2); psoriasis (2); thyrotoxicosis (2); Type 1 diabetes (2); acute GVHD (1); adenocarcinoma (1); allergic rhinitis (1); ANCA-associated vasculitis (1); Angina (1); autism spectrum disorder (1); bladder tumor (1); breast tumors (1); chronic lymphocytic leukemia (1); cognitive decline (1); coronary heart disease (1); Crohn disease (1); diabetic retinopathy (1); Dysmenorrhea (1); eczema (1); endometrial cancer (1); epilepsy (1); female infertility (1).
A further 27 diseases each share a sentence with MICB in 1 paper.